ATM (ATM serine/threonine kinase)
Diseases named in the same sentence as ATM in open-access papers (continued):
Sharing a sentence is not in itself a finding about the gene and the disease.
tumor (continued). "The median age at tumor diagnosis in all affected family members of ATM GV carriers with available data (n = 12) was 45 years." (PMID 41546701, 2026). "ATM and ATR are critical kinases in the DDR process, and disruptions in their signaling pathways are closely associated with tumor cell chemosensitivity." (PMID 41473689, 2025). "After DNA damage induction, SLFN11 selectively inhibits the translation of key DDR repair genes (such as ATR and ATM) by mediating tRNA downregulation, thereby impairing the repair capacity of tumor cells." (PMID 40766331, 2025). "ATM deletion in PDAC models highlights its tumor-suppressive function in pancreas-specific oncogenesis by accelerating tumor growth, promoting EMT, increasing mitotic abnormalities, and causing genomic instability." (PMID 41374970, 2025). "In pancreatic models, the loss of ATM function suggests a more aggressive tumor phenotype by promoting genomic instability, EMT, and quicker tumor growth." (PMID 41374970, 2025). "Several tumor suppressor genes located on chromosome 11q, such as DLG2 and ATM, are frequently lost or repressed in NB, contributing to tumor progression." (PMID 41228232, 2025). "Previous studies have shown that combining ATM inhibitors with DNA-damaging drugs, such as topoisomerase I inhibitors leads to synergistic anti-tumour efficacy." (PMID 40256842, 2025). "Among the PCNA-associated hubs, ATM, HDAC1, and MDM2 showed strong correlations with the infiltration of multiple immune cells, highlighting their roles in tumor–immune interactions." (PMID 40430573, 2025). "In the ATM signaling pathway, a high impact mutation (premature stop codon) in TP53BP1 (VAF = 0.012 in HCC cell line to VAF = 0.019 in HCC tumor) was identified." (PMID 40340757, 2025). "For example, genotoxic therapies activate NF-κB via ataxia-telangiectasia mutated (ATM)-mediated IKK phosphorylation, enabling tumor cell survival despite DNA damage." (PMID 40562870, 2025). "ATM complete inhibition has been shown to make tumor cells more vulnerable to DNA-damaging therapies." (PMID 39853455, 2025). "In this study, we further examined the effect of ATM on tumor growth and intratumoral CD8+ T cell infiltration in BALB/C mice." (PMID 40825766, 2025). "Targeting TET2, either alone or in combination with an ATM inhibitor, significantly suppressed tumor growth, highlighting TET2 as a promising therapeutic target." (PMID 40196510, 2025). "In mouse models with human tumor xenografts, M3541 combined with radiation led to complete tumor regression by inhibiting ATM activity and its downstream signaling." (PMID 40422251, 2025). "We conclude that ATM inhibitor-related induction of senescence in HNSCC cells shapes the tumor micro-environment in way that NK cell phenotype is changed." (PMID 40883442, 2025). "M3541 is a recently developed oral ATM inhibitor that, in preclinical studies, enhanced the sensitivity of various tumor cell lines to ionizing radiation and a topoisomerase inhibitor." (PMID 40422251, 2025).
tumor (continued). "Case 6, which had the highest number of SNVs, had missense mutations in ATM, POLE and BRCA2, as well as known pathogenic mutations from ClinVar in MSH6, RAD50, APC and NF1, likely explaining the high mutational load in this tumor." (PMID 40670673, 2025). "Replacing ATMi, inhibitor of Chk2, a phosphorylation target of ATM, showed similar synergistic inhibition of shGFP H1975 cell (Combination Index: 0.5) and tumor growth of cells." (PMID 40831504, 2025). "These treatments encouraged DNA double-strand breaks (DSBs), but ATM activation enhances repair efficiency, promoting tumour survival." (PMID 40256842, 2025). "In ESCC, the long noncoding RNA SNHG20 drives tumor progression by activating the ATM-JAK-PD-L1 axis." (PMID 41208974, 2025). "Our in vitro findings demonstrate that ATM inhibition, particularly in combination with radiotherapy (RT), significantly reduces tumor cell survival and enhances cellular senescence, suggesting a potential strategy to increase the efficacy of RT in HNSCC." (PMID 40883442, 2025). "Beyond DNA repair, ATM influences tumour metabolism by activating the pentose phosphate pathway, which reduces reactive oxygen species and supports nucleotide biosynthesis and anabolic processes." (PMID 40256842, 2025). "The BRCA1 and BRCA2 genes are tumor suppressors involved in DNA repair through homologous recombination, essential for maintaining chromosome integrity as part of the ATM-mediated DNA repair pathway." (PMID 41077566, 2025). "PALB2 and ATM validate as HGSOC predisposition genes, with 6/8 germline carrier tumours exhibiting biallelic inactivation accompanied by characteristic mutational signatures." (PMID 39794353, 2025). "The observed downregulation of IL-8 following combined radiotherapy and ATM inhibition is particularly interesting given IL-8’s roles in promoting tumor growth, angiogenesis, and immune evasion, including suppression of NK cell function." (PMID 40883442, 2025). "Excessive ROS activate ataxia-telangiectasia mutated (ATM), which promotes activation of TSC2 tumor suppressor through the LKB1/AMPK pathway, leading to suppression of mTORC1, ultimately facilitating autophagy induction." (PMID 41300435, 2025). "MYCN promotes the expression of miR-421, a microRNA that targets the 3′ untranslated region (UTR) of ATM mRNA, leading to decreased ATM protein levels and enhancing tumor cell survival and genomic instability." (PMID 41228232, 2025). "Combination of radiotherapy (RT) and kinase inhibitors of the DNA damage repair system (DDRi), targeting Ataxia Telangiectasia Mutated (ATM) or ATM and Rad3-related (ATR), are promising, but the consequences on tumor cell phenotype are still scarce." (PMID 40883442, 2025). "As ATM becomes downregulated, this decreases overall tumor cells’ ability to detect damaged DNA, likely making them more susceptible to PARP inhibitors." (PMID 40842586, 2025). "Further studies demonstrated that compound induced sustained tumour regression when combined with the PARP inhibitor (Olaparib) in an ATM knockout xenograft model." (PMID 40256842, 2025). "The loss of ATM function in PDAC was related to an elevated radiosensitivity, and platinum-based chemotherapy’s effects are enhanced, allowing tumor cells to accumulate DNA damage more effectively." (PMID 41374970, 2025). "Promoter methylation analysis was conducted for the following tumor-suppressor genes: ATM (NPAT) with four analyzed CpG sites (CpG 1–4), PITX2 (CpG 1–5), RASSF1 (CpG 1–3), PTEN (CpG 1–6), and TIMP3 (CpG 1–6)." (PMID 40371330, 2025).
tumor (continued). "Hereditary cancer syndromes involving mutations in key DNA repair genes such as ATM, XRCC2, and RAD51C underscore the central role of these mechanisms in determining tumor and normal tissue responses to ionizing radiation." (PMID 40725389, 2025). "In this in-house cohort, TCCAs with BRAFV600E combined with additional mutations such as ATM, PTEN or KMT2 family genes exhibited more aggressive clinical features, including larger tumor size and higher rates of LNM." (PMID 40895628, 2025). "To test this, we assessed the tumor-free survival of nPHAfl/fl mice and compared their survival rates with those of control mice with intact ATM in their tumors of genotype nPHAfl/+." (PMID 40244686, 2025). "Tumor growth was significantly reduced in ATM-proficient Mino xenografts treated with NVB compared with vehicle." (PMID 40608419, 2025). ",37TP53 mutations, ATM loss, MDM2 amplification, and cyclin D1 amplification are also shown to occur more frequently in luminal B versus A tumours." (PMID 39921934, 2025). "We observed that triple therapy (comprising Atm inhibitor therapy, anti-PD-1 therapy, and radiotherapy) resulted in a significant reduction in tumor weight, as compared with ATM inhibitor alone." (PMID 40825766, 2025). "For example, inhibition of Chk1 in human tumor cells triggers hyperactivation of ATM, ATR, and caspase-2, leading to apoptosis after DNA damage." (PMID 39861152, 2025). "When a germline ATM mutation is discovered, several centers use paired tumor-normal sequencing to document biallelic inactivation because the clinical impact frequently depends on whether tumors acquire a second hit (such as a loss of heterozygosity or a somatic ATM change)." (PMID 41374970, 2025). "Three patients with KRASMUT PDA achieved SD, of whom one had a tumor with ATM defects, and one had SWI/SNF complex alterations in PBRM1 and ARID1B genes." (PMID 40507311, 2025). "Responders were enriched for MMR-d, BRCA1/2 loss, high TIL density, CDK12 loss, ATM or CHD1 alterations, underscoring the predictive value of a broad tumor-based immunogenic signature." (PMID 40806607, 2025). "ATM’s role extends to hypoxic tumour microenvironments, where it stabilises hypoxia-inducible factor 1-alpha (HIF1α)." (PMID 40256842, 2025). "To investigate the relationship between ATM expression levels and immune cells in the tumor microenvironment, we analyzed data from 198 TNBC samples in GEO data (GSE76124)." (PMID 40825766, 2025). "The results showed that ATM inhibition not only significantly delayed tumor growth, but also effectively enhanced the therapeutic effect of anti-PD-1 therapy and radiotherapy." (PMID 40825766, 2025). "Based on the synergistic reduction of tumor growth of ATM inhibitor AZD0156 and ATR inhibitor VE-822 with a single dose of 1 × 2 Gy13, we first aimed to enhance this effect with a more clinically relevant RT scheme." (PMID 40883442, 2025). "AZD0156, with an IC50 of 0.58 nM, disrupts DNA damage response (DDR) mechanisms and induces apoptosis in ATM-overexpressing tumours." (PMID 40256842, 2025).
tumor (continued). "To date, genetic profiling of BCAC cases has revealed mutation of PIK3CA, ATM, CYLD and NFKBIA14,23, but given the rarity of this tumour type and the small number of genes profiled, the roles of these mutations in tumour development is unclear." (PMID 40389436, 2025). "In vivo, dual ENPP1/ATM inhibition heightened radiosensitivity, compromised tumor cell survival and enhanced STING-TBK1 signaling by preventing ENPP1-mediated cGAMP hydrolysis." (PMID 40506449, 2025). "Integrin-αvβ3 is upregulated on therapy-resistant tumor cells via chronic activation of ATM/Chk2 and NF-κB pathways." (PMID 41208974, 2025). "CtDNA gene detection was concordant with mutations detected via tumor samples and analysis revealed clinically actionable alterations, including EGFR, BRAF, MET, CDK4, CDKN2A, ATM, and CDK6." (PMID 38927984, 2024). "The deletion of ATM signaling causes delayed end resection and repairs single-ended DSBs via NHEJ, resulting in irregular chromosome fusion and tumor cell death." (PMID 38910895, 2024). "Upon hyperthermia-induced DNA damage, tumor cells utilize two primarily distinct kinase signaling cascades to repair DSBs, including the ATM-Chk2 and ATR-Chk1 axes." (PMID 38419081, 2024). "Among genes, we detected to be hypermethylated and silenced in PTCL are major tumor suppressors, e.g. ATM, which plays a critical role in DNA repair and whose functions are often compromised in PTCL through acquired genetic alterations." (PMID 38464090, 2024). "Together, these data indicate that ATM inhibitors in combination with PARPi can be effectively used to overcome drug resistance in H2AX-deficient tumours and control tumour growth." (PMID 38789420, 2024). "Other genes that have been proven to be associated with tumor initiation or progression like PIK3CA, ATM, PTEN, and CREBBP are also present in PDTC and ATC with a mutation frequency higher than 5%." (PMID 39235852, 2024). "Loss of the ATM signal delays terminal excision and repairs the single-ended DSB via NHEJ, resulting in abnormal chromosome fusion and further death of tumor cells." (PMID 39334297, 2024). "Our data strongly argued that GZ17-6.02-induced signaling by ATM plays one of the key causal roles in GZ17-6.02-treated MF cells, enhancing autophagosome formation and subsequently tumor cell killing." (PMID 38329728, 2024). "Downregulating the abundance of TRIM28 in tumor cells can increase the efficacy of radiotherapy, and ATM inhibitor (ATMi) drugs promote the sensitivity of glioma cells to radiotherapy by inhibiting TRIM28 phosphorylation." (PMID 39100077, 2024). "ATM, a potential tumor suppressor in NB, plays a pivotal role in the regulation of apoptosis, cell cycle arrest, and repair of double-strand breaks caused by endogenous genomic stress or exogenous irradiation." (PMID 39338204, 2024). "Researchers have found that miRNAs regulate the expression of EZH2 and ATM genes, promote tumor cell proliferation and invasion." (PMID 38605642, 2024). "Only in patient 2 a pathogenic mutation (according to FATHMM prediction) was found in the regressive tumor lesion in the ATM gene (c.8494C > T)." (PMID 38280045, 2024). "Multiple mechanisms, including NF‐κB signalling, p38MAPK signalling, mTOR signalling, ATM signalling and autophagic activity, have been reported to mediate these regulatory effects in senescent tumour cells." (PMID 39270064, 2024). "BALB/C mice were injected with vector control CT26 cells and ATM-KO CT26 cells to record tumor growth rates after different treatments." (PMID 39033176, 2024). "The most common tumor types were ovarian (n = 23), breast (n = 15), pancreatic (n = 14), and prostate (n = 14); the most frequent enrollment genes were ATM (n = 38), BRCA1 (n = 28), BRCA2 (n = 15), SETD2 (n = 10), and CDK12 (n = 7)." (PMID 38710487, 2024).
tumor (continued). "Patient 212, a pre-menopausal woman with a triple-negative subtype diagnosed at stage 2 and treated with EC, exhibited strong positive immune reactivity for both phosphorylated ATR and ATM in the tumor, correlating with a DFS of 184 months." (PMID 39123356, 2024). "When 22Rv1 ATM−/− tumors reached an average tumor volume ~ 1000 mm3, 2 or 20 μmol/kg MS ~ SN-38 was administered IT." (PMID 38890412, 2024). "In summary, our data demonstrate that BLM-induced MHC-I upregulation in tumor cells relies on ATM/ATR–NF-κB activation." (PMID 39106105, 2024). "It has been suggested that the inhibition of ATM expression can enhance the sensitivity of tumor cells to radiotherapy by preventing ATM-induced activation of ATM-Chk2 and ATR-CHK1 signaling." (PMID 38651153, 2024). "Tumor CGP was performed to investigate additional treatment options, revealing an ATM p.R1875* mutation present at a VAF of 48.2%." (PMID 38898688, 2024). "The radiosensitizing activity of DDP is correlated to DDP-mediated phosphorylation of ATM which results in prosurvival effect on tumor cells." (PMID 38947402, 2024). "Our data suggest that ATM inhibition can improve radiotherapy efficacy by inducing tumor autonomic type I IFNs response and cell lethal stress in CRC." (PMID 39033176, 2024). "Therapy-induced upregulation of PDL-1 and MHC1 on the tumor surface further offers a temporal window of sequential PDL-1 inhibition in combination with anti-ATM agent." (PMID 39100682, 2024). "ATM is a tumor suppressor gene with multiple protein functions, such as DNA-repair and cell cycle regulation." (PMID 39594770, 2024). "A tissue microarray of a single center HNSCC cohort was stained for ATM, DNA-PKcs and Ku80 and the expression scored based on staining intensity and the percentages of tumor cells stained." (PMID 39478631, 2024). "Evaluating the methylation of the patterns of TSG promoter regions using standardized CpG islands in rat tumor cells in vivo treated with salvia showed a significant decline in ATM and PTEN promoters." (PMID 38464730, 2024). "Next, we constructed mouse tumor models treated with KU60019 to evaluate the therapeutic effect of ATM inhibitors." (PMID 39033176, 2024). "Patients with CC tumours are more likely to have deletions at specific chromosomal sites (6q, 8p and 10q) and increased SPOP and ATM mutations." (PMID 39022662, 2024). "Study showed that concurrent radiation and inhibitor of ATM, a DNA damage repair protein, elicits tumor growth inhibition mainly by augmenting STING-dependent IFN1 production and chemokines critical for immune infiltration." (PMID 39100682, 2024). "We have also shown that IT injection of MS ~ SN-38 in 22Rv1 ATM–/– xenografts has anti-tumor activity comparable to a tenfold higher dose of systemically administered SN-38." (PMID 38890412, 2024). "Significant differences in the prevalence of potentially targetable genomic alterations (ATM, BRAF, BRCA2, ERBB2, IDH1, PIK3CA, and PTEN) were observed in MTAP-loss tumors and varied according to tumor type." (PMID 38330461, 2024). "Gene promoter methylation analysis of the following tumor-suppressors was realized: ATM comprising four evaluated CpG sites (CpG 1–4), PITX2 (CpG 1–5), RASSF1 (CpG 1–3), PTEN (CpG 1–6), and TIMP3 (CpG 1–6)." (PMID 38464730, 2024). "And miR‐200/ATM axis has been reported to modulate immune function and blood circulation in tumor and other disease models." (PMID 38385859, 2024). "AZD1390 is a first-in-class ATM inhibitor that radiosensitizes in preclinical tumor models and is under investigation in combination with radiation in phase I clinical trials (NCT03423628, NCT05116254)." (PMID 38376927, 2024).